CDC42 (cell division cycle 42)
Diseases named in the same sentence as CDC42 in open-access papers (continued):
Sharing a sentence is not in itself a finding about the gene and the disease.
pancreatic cancer (33 papers, 2012 to 2025). "We explored the mechanism underlying PGR-induced macropinocytosis in pancreatic cancer and identified CDC42 as a downstream target of PGR." (PMID 38424455, 2024). "A study showed that cell apoptosis, metastasis and Cdc42 pathways were strongly associated with IQGAP3 expression in pancreatic cancer patients." (PMID 32824461, 2020). "It has been demonstrated that MSA can induce entosis in pancreatic cancer cells by cell detachment via the downregulation of two important factors: the cell division control protein 42 homolog (CDC42) and its downstream effector integrin-β1(ITGB1, CD29)." (PMID 36144278, 2022). "Mechanistically, we demonstrated that SKA1 enhanced pancreatic cancer aggressiveness by inhibiting G2/M arrest and regulating actin cytoskeleton organization via activating Cdc42." (PMID 32232899, 2020). "A recent study also proposed that IQGAP3 is a Cdc42 pathway-related protein, since knockdown of IQGAP3 in a pancreatic cancer cell line decreased the expression of Cdc42." (PMID 32824461, 2020). "The most significantly identified enriched pathway were about the pancreatic cancer (P = 0.0011), which four target genes (CDC42, MAPK1, SMAD3, and CDK6) were predicted to be involved in." (PMID 33178707, 2020). "S-nitrosylated proteins in pancreatic cancer pathway identified in this study also include Rac1, Rac2, CDC42, STAT1, and RB, which are all important regulators of pancreatic cancer cells." (PMID 31801946, 2019). "An inverse relationship between cellular adhesion and migration has previously been described for pancreatic cancer cells, where downregulation of p8 promotes cellular adherence and decreases cellular migration via regulation of cdc42." (PMID 31905626, 2019). "ZCL278, as a Cdc42-selective small molecule inhibitor, also can suppress cellular invasion and migration in pancreatic cancer cell lines." (PMID 29596304, 2018). "CDC42 is overexpressed by 21% in pancreatic cancer and the depletion of CDC42 enhances mitotic deadhesion and depends on Rho A activation in human bronchial epithelial cells." (PMID 30241340, 2018). "To choose the best cell line for the study, we first assessed the expression of Cdc42, RhoA and Rac1 in a panel of pancreatic cancer cell lines." (PMID 28410221, 2017). "Pancreatic cancer cells expressing mutant PLXNA1 showed activation of Rho-GTPase CDC42, cofilin, and MAPK signaling which was accompanied by cytoskeletal and expansion disorganization." (PMID 26962861, 2016). "We showed that upregulation of ARHGEF15 in pancreatic cancer increased activation of the Rho-family proteins, especially RhoA, Cdc42 and Rac, resulting in enhanced motility of the pancreatic cancer cells." (PMID 27145964, 2016). "We also found that the depletion of ARHGEF15 by RNA interference in pancreatic cancer cell lines downregulated the activities of molecules of the Rho signaling pathway, including RhoA, Cdc42 and Rac1." (PMID 27145964, 2016). "Cdc42 gene is the common differentially expressed gene in four dysregulated pathways indicating its key role in pancreatic tumour." (PMID 22676414, 2012). "Previous studies showed p-ezrin directly promotes cell mobility and migration in cancer cell lines through the activation of different signaling pathways, including Rac1, CD44 and Cdc42, while in pancreatic cancer ezrin activates FAK/Akt to promote proliferation." (PMID 36926194, 2023). "Interestingly, a β-Pix-CDC42 pathway has recently been identified to regulate perineural invasion in pancreatic cancer." (PMID 34374417, 2021). "In addition, this study revealed that addition of CDC42 decreased Dox sensitivity in NB cells, which is also in agreement with former work that suggested CDC42 enhanced chemoresistance in pancreatic cancer." (PMID 31889909, 2019). "Additionally, we show that both compounds preferentially down-regulate Rac1 activity compared to Cdc42 and RhoA in pancreatic cancer cells." (PMID 28410221, 2017).
pancreatic cancer (continued). "Surprisingly, we found that four crucial microRNAs (miR-34a-5p, miR-195-5p, miR-30c-5p, and miR-130b-3p) regulated the expression of many mRNAs (Cdk4, Cdk6, VEGF, IKKα, MEK1, E2F3, Rac1, E2F1, ERK1, and CDC42) and their proteins, and thus were crucial to the anti-pancreatic cancer effects of DHA." (PMID 27613829, 2016). "Furthermore, a switch from E-cadherin expression to P-cadherin, which is associated with a more invasive behavior, in ovarian and pancreatic cancer cell lines results in the translocation of CTNND1 to the cytosol, which in turn induces cell migration by activating RAC1 and CDC42." (PMID 27193094, 2016). "In pancreatic cancer cells, VAV1 triggers the guanine nucleotide exchange of Cdc42 and is a major driver of invadopodium assembly." (PMID 40126693, 2025). "In pancreatic cancer, palladin induces invadosome formation in CAF and invasion through Cdc42 activity." (PMID 38777849, 2024). "In pancreatic cancer, ITGB1 promotes gemcitabine resistance via CDC42 activation of PI3K p110β signalling." (PMID 33613118, 2021). "PAK4, a dual Cdc42/Rac1 effector, is overexpressed in pancreatic CSCs and functions as an upstream activator of STAT3, which is required for pancreatic cancer stemness." (PMID 32915198, 2020). "Human pancreatic cancer cells were shown to utilize IL‐6‐mediated Jak2‐STAT3 signaling to form a trimeric complex of Cdc42 with its interaction partner IQGAP1 and STAT3 for IQGAP‐mediated activation of Cdc42." (PMID 33960104, 2022). "To determine protein levels of the mRNAs modulated by DHA via microRNAs, we next examined Cdk4, Cdk6, VEGF, IKKα, MEK1, E2F3, Rac1, E2F1, and CDC42 protein levels, which affect growth, inhibit angiogenesis, and promote apoptosis in DHA-treated and vehicle-treated pancreatic cancer cells." (PMID 27613829, 2016). "Moreover, ARHGAP31 is not previously associated with pancreatic cancer, but has well-studied roles in actin modulation, since ARHGAP31 is the human orthologue for the mouse protein CdGAP (mCdc42 GTPase-activating protein) and ARHGAP31 inactivates the GTPases CDC42 and RAC1." (PMID 39110005, 2024).
colon carcinoma (32 papers, 2004 to 2026). "We next investigated the association between Rac/Cdc42 activity and clinicopathological factors in colon cancer." (PMID 35110666, 2022). "Group I p21-activated kinases (PAKs) have been implicated in colon cancer cell transformation in expression and functional studies and are important effectors of the small GTPase Cdc42." (PMID 24279335, 2013). "We investigated the effects of AZA197 treatment on RhoA, Rac1 and Cdc42 activities and associated molecular mechanisms in colon cancer cells in vitro." (PMID 24279335, 2013). "Our data indicate that a strong decrease in Cdc42 and Rac1 activity is clearly associated with increased colon cancer invasiveness." (PMID 23144867, 2012). "MiR-18a can affect the onset of colon cancer through the Cdc42/filopodia pathway, and miR-29a can affect the onset of colon cancer by regulating b-3p-COL5A1." (PMID 36755247, 2023). "Rac/Cdc42 activity was significantly higher in the tumor area than in the normal mucosa in colon cancer patients, especially in the invasive front, increasing its usefulness in the prediction of invasion and metastasis in various types of cancers." (PMID 35110666, 2022). "On the other hand, in the human colon cancer cells we tested, the endogenous activity of Cdc42 appeared to be much lower than that of Rac1 under physiological conditions." (PMID 35110666, 2022). "Under optimal staining conditions, we succeeded in detecting activated Rac and Cdc42 in colon cancer FFPE tissue sections and breast and brain cancers." (PMID 35110666, 2022). "In 50 cases of colon cancer, various activation patterns of Rac/Cdc42 were observed, which were designated plasma membrane, cytoplasm, mixed pattern, and polarized distribution." (PMID 35110666, 2022). "We next examined the intensity and staining pattern of active Rac/Cdc42 staining in mouse xenograft tumors derived from human colon cancer cell lines." (PMID 35110666, 2022). "According to our extensive literature review, studies involving active CDC42 expression in human colon cancers were rarely reported." (PMID 33994856, 2021). "For example, miR-137 inhibits growth, migration, and invasion of gastric and colon cancers by targeting Cdc42." (PMID 34539732, 2021). "In colon cancer cells, leptin activates Rho, Rac and cdc42 which are involved in enhancing migration and invasion." (PMID 33582946, 2021). "CDC42 is overexpressed in a variety of tumor types and is activated by oncogenic Ras protein to instigate Ras-mediated tumorigenesis in colon cancer." (PMID 28589855, 2017). "Activation of Rho GTPase Cdc42 promotes adhesion and invasion in CRC55 and targeting Cdc42 with AZA197 suppresses primary colon cancer growth and prolongs survival in a xenograft model through down regulation of PAK156." (PMID 25990418, 2015). "It is therefore possible that AZA197 inhibition of Cdc42 also affects cell adhesion in addition to impairment of colon cancer cell proliferation, migration and invasion." (PMID 24279335, 2013). "Cdc42 plays an important role in cytoskeleton organization and reducing Cdc42 activity with AZA197 resulted in a loss of filopodia formation and significantly reduced colon cancer cell cell migration and invasion capacity." (PMID 24279335, 2013). "We report here the characterization of a Cdc42-selective small-molecule inhibitor AZA197 for the treatment of colon cancer that was developed based on structural information known from previously developed compounds affecting Rho GTPase activation." (PMID 24279335, 2013). "Targeted silencing of Cdc42 exhibited the importance of this GTPase in motility and invasion of Caco-K cells, suggesting that KRASG12V induces migration and invasion properties in human colon cancer cells through activation of Cdc42." (PMID 21943101, 2011). "Cdc42 was also found to interact directly with both full-length APC and a truncation mutant APC1–1638, which is implicated in colon cancer." (PMID 21311754, 2011).
colon carcinoma (continued). "Localised disruption of E-cadherin-mediated cell–cell adhesion sites was recently observed in invasive human colon carcinoma cells and this disruption was associated with relocalisation of IQGAP1, a Rac1/Cdc42 effector molecule." (PMID 14735193, 2004). "In this study, we designed and characterized a nanoparticle-based delivery system for CASIN encapsulated within poly(lactide-co-glycolide)-block-poly(ethylene glycol)-carboxylic acid endcap nanoparticles (PLGA-PEG-COOH NPs) for targeted inhibition of Cdc42 activity in colon cancer." (PMID 39458630, 2024). "We examined Rac/Cdc42 activity in 50 human colon cancer FFPE tissues (Stage 0–IV)." (PMID 35110666, 2022). "Though CDC42 was reported highly expressed in colon cancer and was downregulated by the potential tumor suppressor gene ID4, its role in the metastasis of colon cancer is still unknown." (PMID 36146640, 2022). "Moreover, a reduction in protein expression levels of phospho-Rac1/Cdc42/Rac1/Cdc42 ratio, Cofilin, Vimentin, and phospho-Paxillin was found in both colon cancer cell lines studied." (PMID 32143529, 2020). "This study demonstrated up-regulated active Rac1, CDC42 and RhoA expression in Hes1-expressing colon cancer cells, whereas down-regulated active Rac1, CDC42 and RhoA expression in Hes1-silencing cells, which indicated that Hes1 induced cytoskeleton reconstruction of colon cancer cells." (PMID 26452029, 2015). "Like Cdc42 and Rac, high protein expression levels of the Rho GTPase RhoA appears to be a frequent event in different types of human tumors, including colon cancer and increased RhoA activity correlates with poor prognosis and recurrence in hepatocellular carcinoma." (PMID 24279335, 2013). "We propose that therapy targeting Rho GTPase Cdc42 signaling pathways may be effective for treatment of patients with advanced colon cancer overexpressing Cdc42 and particularly those with KRAS-mutant disease." (PMID 24279335, 2013). "In this study, we newly found various activation patterns of Rac and Cdc42 in colon cancer FFPE tissues, designated as membrane, cytoplasm, mixed type of membrane and cytoplasm, and polarized patterns, which may demonstrate distinct functions of activated Rac and Cdc42." (PMID 35110666, 2022). "Notably, various activation patterns of Rac/Cdc42 were observed in colon cancer FFPE tissues, designated plasma membrane, cytoplasmic, mixed membrane and cytoplasm, and polarized patterns, suggesting functional variation of activated Rac and Cdc42 in human colon cancer tissues." (PMID 35110666, 2022). "Finally, it is important to state that our findings do not exclude that miR-340-5p might target other molecules, such as RhoC and Cdc42, of potential importance for colon cancer cell migration and invasion." (PMID 33037251, 2020). "Moreover, the finding that inhibition of Cdc42 results in loss of elongated, mesenchymal morphology, which we also observed following AZA197 treatment, further strengthens the function of AZA197 as a Cdc42 inhibitor and the tumor promoting role of Cdc42 in colon cancer." (PMID 24279335, 2013). "Similarly, PAK1/2 phosphorylation was also dose-dependently and significantly reduced up to 72.8 ± 15.8% (P < 0.014) on AZA197 treatment of HT-29 cells without influencing total PAK protein expression, indicating that Cdc42 inhibition blocks the PAK1 signaling pathway in these colon cancer cells." (PMID 24279335, 2013). "It was shown that the Cdc42 inhibitor AZA197 suppressed the proliferation, migration, and invasion of SW620 and HT-29 colon cancer cells and increased apoptosis." (PMID 39458630, 2024). "CDC42/RAC guanine nucleotide exchange factor, βPix, binds to β-catenin in colon cancer cells, augmenting β-catenin transcriptional activity." (PMID 37805544, 2023).
colon carcinoma (continued). "In the YUMC-C1 and YUMC-C2 drug-resistant and metastatic colon cancer cells, respectively, metastatic genes (CDH2, KRAS, CDC42, MCPH1, SRGAP) and markers of stemness (BRACA1 and 2, CD44, KRT5, WNT4, CD29, SAL4) were markedly enhanced." (PMID 33050525, 2020). "Same miRNA can regulate different RHO GTPases, for example miRNA-185 can affect the protein levels of both RHOA and CDC42 in colon cancer cells, or each RHO GTPase is a specific target; miRNA-155 specifically targets RHOA and miRNA-29 targets CDC42." (PMID 31248017, 2019). "We provide evidence that Cdc42 inhibition by AZA197 treatment suppresses proliferative and pro-survival signaling pathways via PAK1-ERK signaling and reduces colon cancer cell migration and invasion." (PMID 24279335, 2013). "The exact molecular signaling pathways mediating this effect are yet to be discovered, however, we have previously found that leptin promotes colon cancer cell metastatic potential by affecting PI3K and Src kinase pathways and activating Rac1 and Cdc42." (PMID 24073224, 2013). "To analyze AZA197 specificity for Cdc42 inhibition, we tested the effects of AZA197 on inhibition of the Rho GTPase family members Rac and Rho, which also play a role in colon cancer." (PMID 24279335, 2013). "In addition, in 50 colon cancer FFPE tissues, Rac/Cdc42 was further activated in the invasion front of the tumor." (PMID 35110666, 2022). "In contrast, stable overexpression of FAM3B-258, a non-secretory form of FAM3B, in colon cancer cells led to increased expression levels of Slug and Cdc42 and promoted cell migration and invasion in vitro and metastasis in nude mice." (PMID 28536423, 2017). "Similarly, over expression of RhoA, Rac1, and Cdc42 all led to induced COX-2 expression in NIH3T3 cells, MDCK epithelial cells, and HT29 colon cancer cells through a NF-κB dependent mechanism." (PMID 26416248, 2015). "We therefore designed the small molecule Cdc42 inhibitor AZA197 and show that inhibition of Cdc42 activity with AZA197 acts to reduce tumor growth and significantly improve animal survival in SW620 cells which are a model of KRAS mutant colon cancer xenografts." (PMID 24279335, 2013). "To analyze signaling pathways that could mediate the effects of AZA197 on Cdc42 inhibition, we examined the activity of the downstream effector PAK by evaluating PAK phosphorylation in SW620 and HT-29 colon cancer cells following AZA197 treatment." (PMID 24279335, 2013). "To test whether the observed decrease in Cdc42 and Rac1 and increase in ROCK activity were both involved in tumour progression to more advanced stages, we treated these three colon cancer cell lines with PDGF to re-activate Cdc42 and Rac1 and/or with Y27632 to block ROCK." (PMID 23144867, 2012). "Thus, inhibition of Cdc42-activity alone without affecting Rac-activity could lead to a potent suppression of colon cancer growth and increased survival rates." (PMID 24279335, 2013). "In the same study, Cdc42 overexpression in SW620 cancer cells down-regulated the potential tumor suppressor gene ID4, further indicating that Cdc42 may play a role in the development of colon cancer and is a suitable target for intervention in patients with this disease." (PMID 24279335, 2013). "In SW620 and HT-29 human colon cancer cells, AZA197 demonstrated selectivity for Cdc42 without inhibition of Rac1 or RhoA GTPases from the same family." (PMID 24279335, 2013).